TLR6 (toll like receptor 6)
Diseases named in the same sentence as TLR6 in open-access papers (continued):
Sharing a sentence is not in itself a finding about the gene and the disease.
atherosclerosis (9 papers, 2013 to 2024). A disease characterized by the build-up of fatty material and calcium deposition in the arterial wall resulting in partial or complete occlusion of the arterial lumen. "Our results shown here indicate an association of the TLR-6 Pro249Ser SNP with the risk for atherosclerosis, and potentially with the risk for restenosis after successful PTCA." (PMID 24498948, 2013). "We found the homozygous mutated TLR-6 genotype to be significantly associated with a reduced susceptibility to atherosclerosis (odds ratio of 0.69, 95% CI 0.51-0.95; P = 0.02)." (PMID 24498948, 2013). "TLR-6 has been shown to mediate inflammatory response by oxLDL, a known risk factor for atherosclerosis." (PMID 24498948, 2013). "It has been reported that in atherosclerosis, 7a-Hydroxycholesterol can elicit TLR6-mediated expression of IL-23 by monocytic cells via PI3K/Akt and MAPKs pathways, leading to inflammation via the upregulation of CCL2 and MMP-9 in macrophages." (PMID 34552973, 2021). "Taken together, our results define a role for TLR-6 and its genetic variations in modulating the inflammatory response leading to atherosclerosis." (PMID 24498948, 2013). "Our results suggest that the less functional TLR-6 Ser/Ser genotype protects from atherosclerosis as well as from restenosis after successful PTCA." (PMID 24498948, 2013). "Having shown that the TLR-6 ser/ser genotype protects from atherosclerosis we could show here that this genotype is increased in the healthy elderly." (PMID 24498948, 2013). "A deficiency in either TLR6 or TLR1 did not reduce atherosclerosis disease induced by exposure to a high fat diet, all together suggesting that TLR6 and TLR1 individually may not be sufficient per se, but will act together with TLR2 as heterodimers." (PMID 23880853, 2013). "OxLDL has been shown to induce Cxcl1 expression in macrophages via a co-operation of CD36/TLR4/TLR6, and CXCL1 represents a key mediator of leukocyte recruitment in atherosclerosis." (PMID 26947073, 2016). "Studies have found that a heterodimer of TLR4 and TLR6 promote a protracted sterile inflammatory response after being triggered by oxidized low-density lipoprotein (LDL) and β-amyloid, which involves the pathogenesis of atherosclerosis and Alzheimer’s disease." (PMID 35126357, 2021). "New developments in the basic understanding of the roles of TLR3, TLR6 and TLR7 from in vitro studies and pre-clinical models of disease may open up new avenues of TLR-targeted therapy for atherosclerosis." (PMID 23880853, 2013).
colitis (9 papers, 2007 to 2025). Inflammation of the colon. "Clearly, although our data suggest dectin-1 signalling is redundant in intestinal inflammation TLR2 and/or TLR6 deficiency does affect experimental colitis via separate mechanisms indicating that dectin-1 deficiency does not seem to affect TLR signalling." (PMID 22507600, 2012). "Interestingly, we observed that TLR1−/− and TLR2−/− mice were more susceptible to DSS-induced colitis than TLR6−/− and wild-type mice." (PMID 28289440, 2017). "TLR6−/− mice were more resistant to DSS-induced colitis as reflected by lower clinical and histologic scores for inflammation and mortality." (PMID 28289440, 2017). "The aim of this study was to determine the impact of TLR1, TLR2, and TLR6 deficiency on inflammatory parameters associated with C. albicans colonization and acute colitis induced by DSS by comparing wild-type, TLR1−/−, TLR2−/−, and TLR6−/− mice." (PMID 28289440, 2017). "Reduced DSS‐induced colitis via TLR6 signaling and gut microbiota modulation." (PMID 41273201, 2025). "In this study, we explored whether the deficiency in TLR1, TLR2 or TLR6 impacts C. albicans colonization and inflammation-associated colonic injury in the dextran sulfate sodium (DSS)-induced colitis in mice." (PMID 28289440, 2017). "Additionally, a recent study demonstrated that Tlr1 and Tlr2 (but not Tlr6) knockout mice display increased intestinal permeability and pathogenic yeast colonisation in a colitis model." (PMID 37997696, 2023). "In the present study, we showed that in contrast to the state of TLR6−/− mice, DSS-induced colitis induced the production of pro- and anti-inflammatory cytokines, including IL-10, in TLR1−/− mice." (PMID 28289440, 2017). "Importantly, the clinical symptoms of colitis, such as diarrhea and bloody stools, appeared more rapidly in TLR1−/− and TLR2−/− mice than in wild-type and TLR6−/−C." (PMID 28289440, 2017). "However, another group reported that TLR6 was overexpressed in the intestines of IBD patients and might promote experimental colitis in mice." (PMID 29441063, 2018). "In this context, it is tempting to speculate that HIF-dependent induction of TLR2 and TLR6 may be part of hypoxia-elicited innate protection during epithelial inflammation and treatment with HIF-activators (such as DMOG) may be protective during colitis via TLR2 induction and signaling." (PMID 18159247, 2007). "However, DSS-induced colitis promoted an increased E. coli population in TLR1−/−, TLR2−/− and wild-type mice, but a decrease in TLR6−/− mice, regardless of C. albicans colonization." (PMID 28289440, 2017).
malaria (8 papers, 2011 to 2025). Malaria is a serious and sometimes fatal disease caused by a parasite that commonly infects a certain type of mosquito which feeds on humans. "Dysregulation of TLR6 signalling has also been widely implicated in a range of diseases, such as ulcerative colitis and mild malaria." (PMID 40869997, 2025). "An association of polymorphisms in TLR1 and TLR6 with mild malaria in patients infected with different Plasmodium species was recently demonstrated." (PMID 28850598, 2017). "At TLR6 N249S (rs5743810), which is associated with variation in resistance to malaria, the allele that confers resistance occurs at high frequency in Africa and Asia and lower frequency in European populations." (PMID 21533023, 2011). "In addition, SNPs I602S (TLR1) and S249P (TLR6) were associated with severe malaria in Indian patients, showing the genetic contribution of these variants to the onset of cerebral malaria." (PMID 28850598, 2017). "Genetic variation in TLR1 and TLR6 could alter the risk of development of complicated malaria and ability of the host to control the parasite burden during acute Plasmodium falciparum infection." (PMID 26738805, 2016). "Given the likelihood that associations between TLR1 or TLR6 genotype frequencies and malaria phenotypes would be confounded by major underlying population differences in genetic architecture, analyses for the Karen subjects were performed separately from the other ethnic groups." (PMID 26738805, 2016). "However, taken together, these studies suggest that genetic variation in TLR1 affects host susceptibility to malaria disease severity, while variation in TLR6 is less likely to play a significant role in these processes." (PMID 26738805, 2016). "The TLR6 S249P polymorphism may be a risk factor for the development of malaria." (PMID 28850598, 2017). "Functional genetic variation within TLR1 and TLR6 could therefore be associated with severity of malarial illness and/or the degree of parasitaemia observed in each patient on the day patients were diagnosed with clinical malaria." (PMID 26738805, 2016). "Testosterone pre-treatment amplifies TLR6 expression 5.6-fold and suppresses TLR8 expression 6.5-fold, suggesting dysregulated TLR6 and TLR8 signaling contributes to increased malaria susceptibility." (PMID 39492784, 2024). "Malaria is an infectious disease that also requires TLR1/2, TLR4, and TLR6 to form an immune response." (PMID 36313452, 2022).
viral infection (8 papers, 2013 to 2025). "The herbs offered potential resistance to viral infections in birds by stimulating macrophage production, as well as T-cell-mediated immune responses and stimulating macrophages through TLR6 signaling and NF kappa B translocation, leading to cytokine production." (PMID 35017836, 2021). "In this study, we focused on TLR1, TLR2, TLR4, TLR5, TLR6 and TLR9 expression fold changes in two genital epithelial cells (HEC-1-A and VK2) after viral infection." (PMID 30419930, 2018). "In addition, it has been reported that the participation of TLR6, TLR2, and TLR7 actively participates against some viral infections, such as the SARS-CoV-2 virus, which is recognized by TLR2 and subsequently by TLR7 for an effective antiviral response." (PMID 40573281, 2025).
Sepsis (7 papers, 2021 to 2025). Sepsis is defined as life-threatening organ dysfunction caused by a dysregulated host response to infection. "In summary, miR-494-3p attenuates the inflammatory response associated with sepsis by affecting TLR6 expression." (PMID 36012630, 2022). "miR-494-3p seems to attenuate the sepsis-associated inflammatory response by controlling TLR6 expression." (PMID 36012630, 2022). "Another miR, the MIR-494-3p, has been shown to interact with TLR-6 (toll-like receptor 6), disrupting the inflammatory pathway, and the same miR was found to be down-regulated in sepsis while TLR-6 was up-regulated." (PMID 39335561, 2024). "For example, plasma levels of miR-494-3p were observed to decrease in patients with sepsis compared to healthy controls; this process correlates with increased levels of TLR6." (PMID 36012630, 2022). "For example, circulating miR-494-3p levels are decreased in sepsis patients compared to controls, while TLR6 is simultaneously upregulated." (PMID 36012630, 2022). "For instance, plasma levels of miR-494-3p have been shown to be decreased in sepsis patients compared with healthy controls in correlation with up-regulation of TLR6." (PMID 34956235, 2021). "Correlation between PD-1 and TLR-6 in the late stages of sepsis supports the hypothesis that both may play a synergistic role affecting the histopathological status and functionality of lung tissue." (PMID 40076895, 2025).
prostate carcinoma (6 papers, 2009 to 2026). A carcinoma that arises from epithelial cells of the prostate gland. "Additionally, TLR1 and TLR6 are located within the same gene cluster and polymorphisms in these genes have been reported to increase advanced prostate cancer risks." (PMID 30388713, 2018). "Within those sub-pathways, 5 genes (TLR1, TLR6, OAS1, OAS2, and COX-2) were nominally associated with advanced prostate cancer risk." (PMID 23272139, 2012). "Two sub-pathways (intracellular antiviral molecules and extracellular pattern recognition) and four genes in these sub-pathways (TLR1, TLR6, OAS1, and OAS2) were nominally associated with advanced prostate cancer risk and harbor several SNPs nominally associated with advanced prostate cancer risk." (PMID 23272139, 2012). "To date, few pathologies have been genetically associated to TLR2 variants; an increased risk to develop prostate cancer has been traced to TLR1 (and TLR6 and 10 which are located on the same chromosomal locus, and more recently, resistance to leprosy was linked to the frequent I602S TLR1 allele." (PMID 19924287, 2009). "We observed that TLR2, TLR6, and CD14 mRNA were expressed in prostate epithelial cell lines as well as in prostate cancer cell lines, and that these mRNAs were directly related to intracellular signaling upon stimulation with LTA in the human prostate." (PMID 26649771, 2015).
allergic disease (5 papers, 2005 to 2020). An immune response that occurs following re-exposure to an innocuous antigen, and that requires the presence of existing antibodies against that antigen. "One is located near the toll like receptor 6 (TLR6) gene, which functionally interacts with toll-like receptor 2, and is associated with an increased risk of other allergic diseases." (PMID 26941931, 2015). "In addition, numerous SNPs in the gene of TLR6 were reported to be associated with allergic disease." (PMID 33066754, 2020). "Further studies of the TLR6 Ser249Pro polymorphism in ethnically well-defined cohorts as well as functional studies of this variation are warranted to evaluate its role in the pathogenesis of allergic diseases." (PMID 16188043, 2005). "We are aware of only one previous study that examined the interaction between TLR6 SNPs and proxies of microbial exposure and allergic disease outcomes." (PMID 28262750, 2017). "Expression of TLR6 has been demonstrated in human mast cells which play an important role in allergic diseases." (PMID 16188043, 2005). "While several studies have evaluated the role of variation in TLR4, the receptor for endotoxin, for allergic diseases, little is known about the role of TLR6 variation so far." (PMID 16188043, 2005). "In addition, since TLR6 and IL2 were earlier associated with other later onset allergies, this also favours the “allergic march” hypothesis." (PMID 26941931, 2015). "Current studies indicates that genetic variation of TLR6 and IL2, which were earlier reported to be associated with non-CMA allergies and/or allergy sensitization, contribute to the expression of CMA in young children." (PMID 26941931, 2015).
pneumonia (5 papers, 2016 to 2022). An acute, acute and chronic, or chronic inflammation focally or diffusely affecting the lung parenchyma, caused by an infection in one or both of the lungs (by bacteria, viruses, fungi, or mycoplasma.). "In particular, further research is required into the roles of TLR2 or TLR6 polymorphisms in pneumonia." (PMID 36428390, 2022). "The aged mice also express lower levels of TLR1, TLR6, and TLR9 in the lungs, which also increases their susceptibility to pneumonia." (PMID 32849610, 2020). "During pneumonia, AECs recognize various pathogens due to the expression of different PRRs, including TLRs [TLR1, TLR2, TLR4, TLR5, TLR6 (Extracellular TLRs), and TLR3, TLR7, TLR8, and TLR9 (Intracellular TLRs)] and NLRs comprising inflammasome." (PMID 32849610, 2020).
breast carcinoma (4 papers, 2017 to 2026). "These SNPs cause TLR6 to function abnormally, leading to the induction of breast cancer." (PMID 37232814, 2023). "Herein, we evaluated the association of the Toll-like receptor 6 (TLR6) single nucleotide polymorphisms (SNPs) rs3796508 (Val327Met) and rs5743810 (Ser249Pro) with breast cancer (BC) susceptibility in Saudi Arabian women, using in silico analysis." (PMID 30388713, 2018). "In this regard, it was noted that, apart from TLR6, TLR7, and TLR8, the expression levels of the other TLRs were lower in breast cancer tissues compared to normal tissues." (PMID 41550509, 2026). "Consequently, TLR-3, TLR-6, TLR7/8, and TLR-9 agonists are considered among the most promising immunotherapeutic agents for breast cancer treatment." (PMID 41550509, 2026).
leprosy (4 papers, 2009 to 2023). Leprosy is a chronic infectious disease affecting primarily the skin and peripheral nervous system. "The evaluated SNVs show that the rs5743618 variant in the TLR1 gene, in combination with the rs5743708 SNV in the TLR2 gene and the rs5743810 SNV in the TLR6 gene, are related with the susceptibility to leprosy in this population." (PMID 37888601, 2023). "In conclusion, this study is the first to show that the rs5743810 variant of the TLR6 gene is associated with resistance to the development of leprosy in men from the analyzed Colombian population, which is differs from the results reported for the widely studied Asian population." (PMID 37888601, 2023). "Moreover, genetic variants in TLR1, TLR2, TLR4, and TLR6 genes have been associated with autoimmune, infectious and inflammatory diseases, such as leprosy, pulmonary tuberculosis, atopic dermatitis, and systemic lupus erythematosus." (PMID 35141236, 2021). "A case–control study was conducted in a leprosy endemic region of Colombia (Norte de Santander) to investigate the potential association between single nucleotide variants of the TLR1, TLR2 and TLR6 genes and the development of leprosy." (PMID 37888601, 2023). "However, when data were adjusted by age, we found the rs5743810 SNV in TLR6 entailed resistance to leprosy development in men." (PMID 37888601, 2023). "Additionally, we observed that a classification of leprosy patients is possible using transcriptomics since a set of genes were increased in BL/LL patients (CD46, CXCL10, FCGR1A, HDAC2 and TLR4) and TT/BT showed a higher expression of IL2 and TLR6." (PMID 31784594, 2019).
Obesity (4 papers, 2016 to 2025). Accumulation of substantial excess body fat. "Therefore, we could assume that deregulated TLR6 expression and activity may potentiate the chronic low-grade pro-inflammatory state associated to obesity, in parallel with the events taking place in the liver, which eventually determine NAFLD severity." (PMID 27834919, 2016). "In summary, we found deregulated expression of TLR6 with a concomitantly activated downstream TLR2/TLR6 activity towards the expression of pro-inflammatory cytokines in peripheral blood cells and in hepatocytes from obesity-related NAFLD patients." (PMID 27834919, 2016). "Deregulated expression and activity of peripheral TLR6 in morbidly obese patients can mirror the liver inflammatory events that are well known drivers of obesity-related NASH pathogenesis." (PMID 27834919, 2016). "Future investigation of the effects of TLR6 on NAFLD may point to TLR6 as a biomarker for obesity-related NAFLD." (PMID 40076851, 2025). "Dysregulated peripheral TLR6 expression and activity in morbidly obese patients may reflect the well-known hepatic inflammatory event drivers of obesity-related NAFLD pathogenesis." (PMID 40076851, 2025). "Finally, TLR6 overexpression in peripheral blood cells can offer the opportunity to develop non-invasive tools to support the diagnosis of obesity-related NASH." (PMID 27834919, 2016). "Our aim is to study a potential role of TLR6 in obesity-related NAFLD." (PMID 27834919, 2016). "Nevertheless, we cannot exclude that the deregulated expression and functionality of TLR6 could be a consequence of the pro-inflammatory state related to obesity and the liver disease more than the trigger." (PMID 27834919, 2016). "TLR6 could be a potential peripheral biomarker of obesity-related NAFLD." (PMID 40076851, 2025). "Despite the role that TLR2 plays in obesity-related NAFLD, the role of TLR6 in this disease remains unveiled." (PMID 27834919, 2016). "TLR6 expression in B cells, T cells and monocytes was found significantly higher in patients with NASH, compared to those with normal liver biopsies or NAFL, which can reflect the potential of this receptor as a peripheral biomarker of obesity-related NASH." (PMID 27834919, 2016). "Moreover, it is also possible that detecting increased levels of TLR6 expression in peripheral blood (see Figure 1A2) could serve as a non-invasive method to screen for patients that could potentially make progress towards more aggressive forms of obesity-related NAFLD." (PMID 27834919, 2016). "TLR6 is significantly overexpressed in hepatocytes from NAFLD morbidly obese patients compared to non-obese patients, suggesting that deregulated TLR6 may potentiate liver inflammation in obesity." (PMID 40558558, 2025). "Thus, deregulated TLR6 expression may potentiate TLR2-mediated liver inflammation in NAFLD pathogenesis, and also serve as a potential peripheral biomarker of obesity-related NASH." (PMID 27834919, 2016).